RNU6-153P (RNA, U6 small nuclear 153, pseudogene)
Gene: Small nuclear RNA gene on chromosome 6 (166,209,403 to 166,209,506, forward strand). Ensembl gene ENSG00000201292.
Homologues: Orthologues: macaque U6 (96% identical), chimpanzee U6 (95% identical), guinea pig U6 (63% identical), dog U6 (54% identical). Paralogues in human: RNU6-21P (82% identical), RNU6-80P (82% identical), RNU6-214P (81% identical), RNU6-737P (81% identical), RNU6-1013P (80% identical), RNU6-128P (80% identical), RNU6-1316P (80% identical), RNU6-38P (80% identical), RNU6-438P (80% identical), RNU6-61P (80% identical), RNU6-854P (80% identical), RNU6-936P (80% identical), and 1288 more.